TBL1Y (transducin beta like 1 Y-linked)
Description:
F-box-like protein involved in the recruitment of the ubiquitin/19S proteasome complex to nuclear receptor-regulated transcription units. Plays an essential role in transcription activation mediated by nuclear receptors. Probably acts as integral component of corepressor complexes that mediates the recruitment of the 19S proteasome complex, leading to the subsequent proteasomal degradation of transcription repressor complexes, thereby allowing cofactor exchange (By similarity).
Synonyms: TBL1; DFNY2
Tractability: PROTAC: UniProt records ubiquitination sites on it; ubiquitination databases record sites on it.
Gene: Protein-coding gene on chromosome Y (6,910,686 to 7,101,970, forward strand). Ensembl gene ENSG00000092377.
Subcellular location: Nucleus
Subcellular location (Human Protein Atlas): Nucleoplasm
Gene Ontology:
Molecular function: protein binding; transcription corepressor activity
Biological process: regulation of transcription by RNA polymerase II; negative regulation of DNA-templated transcription
Cellular component: nucleoplasm; nucleus; histone deacetylase complex
Homologues: Orthologues: macaque TBL1Y (94% identical), mouse Tbl1x (93% identical), rat Tbl1xr1 (93% identical), guinea pig TBL1X (93% identical), dog TBL1X (93% identical), tropical clawed frog tbl1x (89% identical), chimpanzee TBL1Y (87% identical), zebrafish tbl1x (81% identical), Drosophila melanogaster ebi (73% identical). Paralogues in human: TBL1X (91% identical), TBL1XR1 (84% identical).
Diseases named in the same sentence as TBL1Y in open-access papers:
TBL1Y is named in the same sentence as 10 diseases in open-access papers, as found by Europe PMC text mining. Sharing a sentence is not in itself a finding about the gene and the disease. The quoted sentences say what the papers report.
hearing loss (4 papers, 2019 to 2024). "One of the variants of the TBL1Y gene is considered to be a potential cause of hereditary hearing loss." (PMID 36831738, 2023). "TBL1Y, a highly expressed gene in the prostate, is suggested to be critical in the cardiac differentiation and syndromic hearing loss." (PMID 35120273, 2022). "Moreover, one of the variants of the TBL1Y gene is considered to be a potential cause of hereditary hearing loss." (PMID 36831738, 2023). "TBL1Y (OMIM: 400033), located at Yp11.2, is involved in syndromic hearing loss (Y-linked deafness-2)." (PMID 31828149, 2019).
epilepsy (1 paper, 2025). A brain disorder characterized by episodes of abnormally increased neuronal discharge resulting in transient episodes of sensory or motor neurological dysfunction, or psychic dysfunction. "RNA-seq analysis of the iPSCs revealed that genes such as TTTY14, TBL1Y, MEG8, MEG9, BCORP1, and RPS4Y1 are not directly related to epilepsy." (PMID 40600194, 2025).
cancer (1 paper, 2025). A tumor composed of atypical neoplastic, often pleomorphic cells that invade other tissues. "Here, we found nonsynonymous variants impacting AMELY, DDX3Y, RPS4Y2, and TBL1Y in five African tumors (4.7%), and UTY in a single European tumor (1.8%), highlighting the potential for these chrY genes as ancestry-specific cancer driver candidates." (PMID 40454088, 2025). "Conversely, TBL1Y has not been reported to play a role in cancers but rather cardiac development and hearing loss, however, gene expression is primarily in the prostate and cochlea in adults." (PMID 40454088, 2025).
neurological diseases (1 paper, 2025). "Specifically, we chose the genes TTTY14, TBL1Y, MEG8, MEG9, BCORP1, and RPAS4Y1 for analysis, all of which were found to be unrelated to neurological diseases." (PMID 40600194, 2025).
tumor (1 paper, 2025). "Nonsynonymous mutations were found in the genes AMELY, DDX3Y, RPS4Y2, TBL1Y in African tumors (5 samples: 4 HRPCa 1 LRPCa), and in UTY in one European HRPCa tumor." (PMID 40454088, 2025).
TBL1Y also shares sentences with these, for which no sentence is quoted: amelogenesis imperfecta (1 paper); gastric cancer (1); male infertility (1); spermatogenic failure (1); Y-linked deafness-2 (1).